SNORD28B (small nucleolar RNA, C/D box 28B)
Gene: Small nucleolar RNA gene on chromosome 6 (156,378,750 to 156,378,824, forward strand). Ensembl gene ENSG00000212295.
Gene Ontology:
Biological process: RNA processing
Cellular component: nucleolus
Homologues: Orthologues: chimpanzee SNORD28 (100% identical), macaque SNORD28 (95% identical), pig SNORD28 (72% identical), tropical clawed frog SNORD28 (60% identical). Paralogues in human: SNORD28 (84% identical), SNORA108 (63% identical).